INS (insulin)
Diseases named in the same sentence as INS in open-access papers (continued):
Sharing a sentence is not in itself a finding about the gene and the disease.
Obesity (continued). "Moreover, micronutrients may also exacerbate obesity-related metabolic consequences, impairing insulin signaling and dysregulating glycemic control; vitamins A, B1, B6 and B12, as well as selenium and zinc, have been reported to be low in the plasma of obese individuals." (PMID 37894869, 2023). "The summarized evidence suggests that metformin can reduce body weight, enhance insulin sensitivity, and improve glucose metabolism by promoting BAT thermogenic activity in preclinical models of obesity." (PMID 36768561, 2023). "In subjects with cardio-metabolic diseases such as overweight, obesity, or prediabetes, an AGE-restricted diet reduced some inflammatory markers and improved insulin sensitivity." (PMID 36900799, 2023). "On the other hand, among the obesity classes, people with class 3 obesity presented the highest FFM, HbA1c, insulin, and diastolic blood pressure (DBP), and the lowest HDL-c." (PMID 37334132, 2023). "Interestingly, in adolescents with obesity and high circulating palmitate concentrations, the accentuated first-phase insulin secretion observed in young children was replaced by the delayed and attenuated first phase but the accentuated second phase of insulin secretion was maintained." (PMID 37623862, 2023). "Mice carrying K268R/K293R mutations, mimicking constitutive deacetylation (the 2KR model), are protected from obesity and, more importantly, resistant to TZD’s adverse effects, while retaining the insulin sensitization response." (PMID 37408258, 2023). "Within the brain, obesity could lead to a broad spectrum of homeostatic disruptions such as higher incidence of oxidative stress, inflammation, protein aggregation, mitochondrial dysfunction, altered hormone levels, insulin resistance, and blood-brain barrier (BBB) compromise." (PMID 38026693, 2023). "The beneficial effect of TZT in T2DM and obesity is related to direct activation of GIP and GLP-1 receptors with subsequent improvement of insulin sensitivity and reduction of body weight." (PMID 37208555, 2023). "Dysregulated glucose metabolism due to failure of pancreatic β-cells to secrete sufficient insulin is the main culprit of T2DM and results in patients experiencing hyper- and hypoglycaemic events, accompanied by obesity." (PMID 39184263, 2023). "It was this important observation that proinflammatory TNF-α was highly expressed within adipose tissue in several rodent models of obesity and, when TNF-α was neutralised, insulin action was enhanced." (PMID 37627482, 2023). "Restoring the normal expression of DNAJB3 attenuated metabolic stress and improved insulin signaling both in vivo and in vitro, suggesting a protective role of DNAJB3 against obesity and T2D." (PMID 37895206, 2023). "The beneficial effect of TZT in T2DM and obesity is related to the direct activation of GIP and GLP-1 receptors with subsequent improvement of insulin sensitivity and reduction of bodyweight." (PMID 37208555, 2023). "In animal models, during obesity development, IL6 production in adipose tissues is consistently elevated, especially in insulin-resistance adipocytes." (PMID 37298352, 2023). "Drugs such as insulin, which are related with APE1/Ref-1 reduction or the use of E3330, inhibiting APE1/Ref-1 redox function, would promote adipocyte differentiation or obesity, which should be considered in the new therapeutic target." (PMID 36834665, 2023). "Further analysis revealed that the increased levels of adipose tissue-derived miR-548ag after the onset of obesity upregulated the expression of DPP4 by suppressing DNMT3B in the liver, leading to abnormal glucose tolerance and decreased insulin sensitivity." (PMID 36769291, 2023). "Conditions, in which the hypothalamic MAPK pathway is compromised, as is the case in obesity, can result in impaired regulation of lipolysis and WAT insulin action, leading to ectopic lipid accumulation, lipotoxicity and insulin resistance." (PMID 37100238, 2023).
Obesity (continued). "The mean weight, BMI, BMI z-score, fasting glucose level, insulin level, and HOMA-IR value of the group with overweight/obesity increased significantly from the 2007–2010 dataset to the 2019–2020 dataset in both sexes." (PMID 37443273, 2023). "When classifying the group of children with obesity according to ALT, the upper tercile showed the highest values for insulin, HOMA-IR, TG." (PMID 36894963, 2023). "After 6 months of HIIT (running, 85%–95% HRmax, 2 sessions/week), AFABP significantly decreased and correlated with fasting insulin, HOMA-IR, and triglycerides in adolescents (mean age 15.5 years) with obesity." (PMID 37608837, 2023). "Disorders of insulin, IGF-1, sex hormones, adipokines and inflammatory factors have been observed in numerous studies in the presence of obesity." (PMID 36755926, 2023). "Short-term combined treatment with beinaglutide and metformin appears superior to metformin monotherapy in lowering body weight, BMI, WC,WHtR and improving insulin sensitivity and androgen excess in women with PCOS and obesity, with tolerable adverse events." (PMID 37347114, 2023). "Proinflammatory cytokine levels in circulation are increased during obesity, which induces Ser/Thr phosphorylation of IRS and inhibits insulin signaling by activating JNK and IKKβ." (PMID 37960324, 2023). "On the other hand, obesity can contribute to T2DM through altered pancreatic hormone secretion, impaired glucose uptake in skeletal muscles, and hepatic insulin resistance." (PMID 37299460, 2023). "Adjusting the influence of confounders including obesity (BMI, WHR, WC and HC) and IR (represented by fasting insulin) in mvMR analysis, we found that it was disappeared for the causal relationship between genetically predicted PCOS and 25OHD (P > 0.05)." (PMID 36967791, 2023). "According to the literature, ghrelin levels are decreased in patients with obesity and T2DM compared to eutrophic individuals, due to insulin-inhibitory effects on secretion." (PMID 37252699, 2023). "Correlations between TSH and cholesterol, triglycerides, insulin, and HOMA-IR were previously observed in a cohort of children with obesity as well as in a longitudinal study of children with obesity showing a high-normal range of TSH levels." (PMID 37265695, 2023). "Regarding cardiometabolic indices, compared to MetS-free participants, those with MetS exhibited higher BMI, WC, obesity rates, SBP, DBP, fasting glucose, insulin, HOMA-IR, TG, and hsCRP, and lower HDLC and adiponectin (all P < 0.050)." (PMID 37322405, 2023). "During obesity, dysregulation of the ECS contributes to visceral fat accumulation and suppresses the synthesis of adiponectin, decreasing insulin sensitivity and fatty acid oxidation." (PMID 36830844, 2023). "Thus, both acute hyperinsulinemia driving Akt and mTORC1 activity, as well as an altered insulin resistant macrophage during chronic obesity with increased basal glycolysis and mTORC1 activity, might both facilitate downstream effects known to induce trained immunity." (PMID 36992811, 2023). "Similar effects of reduced insulin hypersecretion and dyslipidemia are observed with REG3A transgenic mice during aging and obesity after feeding with a high-fat diet." (PMID 36918710, 2023). "Obesity-induced inflammatory cytokines, particularly tumor necrosis factor-α (TNF-α), also impair insulin signaling via the serine phosphorylation of IRS-1." (PMID 36671511, 2023). "Ovarian and endometrial cancer are also associated with obesity, especially in postmenopausal women, due to hormonal changes affecting insulin and IGF-I, all of which are increased in obesity." (PMID 37405618, 2023). "In summary, SR1664 improved insulin sensitivity and reduced fibrosis in the HFHC diet, suggesting selective PPARγ modulation is effective in obesity-related liver fibrosis." (PMID 37886997, 2023).
Obesity (continued). "Children with obesity had higher LDL, n-HDL, insulin, HOMA and alanine aminotransferase (ALT) values than healthy controls; conversely, HDL levels were lower in children with obesity." (PMID 37653524, 2023). "Insulin levels in the HFD, in which obesity was induced by eating a high-fat diet, were increased, compared to the ND." (PMID 37432154, 2023). "A small molecule drug LM22A-4 led to increased AKT phosphorylation and partially rescued locomotor activity, insulin intolerance, and HDL levels, while delaying the onset of obesity in SMS mice." (PMID 37956053, 2023). "Developing strategies to prevent obesity (and indirectly CRC) by regulating insulin production and activating insulin/IGF signaling, and also by understanding the mechanisms of autophagy, is one of the most important challenges today." (PMID 36835075, 2023). "The preoperative and postoperative 6th month body mass index (BMI), TG, total cholesterol, VLDL, HDL, insulin, HgbA1c, TSH, T4, and afamin levels of the patients who underwent bariatric surgery with obesity were compared." (PMID 36769494, 2023). "The results showed that B. coagulans T4 and L. paracasei TD3, alone and in combination with each other, significantly decreased body weight and ameliorated obesity-related oxidative and inflammatory parameters, such as serum TG, FBG, and insulin levels." (PMID 38116571, 2023). "Overexpression of adiponectin in the ob/ob mouse model of obesity exacerbates total weight gain, primarily as a consequence of increased SAT volume, decreases adipocyte diameter in SAT, and normalizes insulin sensitivity and hepatic lipid content." (PMID 36782211, 2023). "In obesity, T2DM and NAFLD, hyperinsulinemia and dysregulated insulin signaling occurs when insulin and IGF-1 bind to their respective receptors and activate PI3K/Akt signaling, a key oncogenic pathway for metabolism, cell growth and cell survival." (PMID 37361533, 2023). "Individuals diagnosed with obesity according to BMI were characterized by significantly higher blood concentrations of such biochemical parameters as TC, TG, LDL-C and HDL-C, insulin, and HOMA-IR index compared to those with normal BMI." (PMID 37887427, 2023). "Methylsulfonylmethane also enhanced the insulin sensitivity and significantly suppressed the HFD-induced obesity and hepatic steatosis in mice." (PMID 38099147, 2023). "Here, this work shows that adipose Mettl3 and Mettl14 are influenced by fasting, refeeding, and insulin, and are upregulated in high fat diet (HFD) induced obesity." (PMID 37526326, 2023). "Hyperinsulinemia, elevated circulating insulin levels in relation to blood glucose levels, was several-fold elevated in children with obesity of the ULSCO cohort, including first and second phase insulin secretion, compared to normal-weight children." (PMID 37623862, 2023). "DS0908 and DS0950 also improved insulin sensitivity and glucose use in mice with HFD-induced obesity." (PMID 36457182, 2023). "Elevated levels of Gremlin 1 in obesity may theoretically account for the decreased volume of beige and/or brown adipose tissue in obesity, and possibly a reduced glucose-buffering capacity of beige and/or brown adipose tissue, resulting in reduced insulin sensitivity." (PMID 37965235, 2023). "Considering the close relationship between glycolipid metabolism and obesity, we measured FBG, fasting insulin, OGTT, and HOMA-IR index values." (PMID 37513467, 2023). "The need of the moment is to develop strategies to help prevent obesity (and indirectly CRC) by regulating insulin and insulin/IGF signaling." (PMID 36835075, 2023). "Most amino acids were increased in obesity subjects and were confirmed among people with nonalcoholic fatty liver disease (NAFLD) subjects due to increased insulin resistance and protein catabolism." (PMID 37308902, 2023). "The METS-IR has attracted increasing attention in recent years as a novel non-insulin-based index considering FPG, blood lipid profiles, and obesity index." (PMID 36673809, 2023).
Obesity (continued). "In this study, we measured inflammatory biomarkers between two distinct insulin resistant populations related to AT dysfunction: one with FPLD2 and the other with obesity." (PMID 37081489, 2023). "The current meta-analysis suggests that exercise training has beneficial effects on fasting glucose and insulin levels, HOMA-IR, and BW in children and adolescents with overweight or obesity." (PMID 37635963, 2023). "The effects of elevated BMI and obesity alter cardiac hemodynamics and probably contribute to the development of LVH in this cohort through systemic inflammation, insulin resistance, and subsequent cardiac remodelling, termed obesity cardiomyopathy." (PMID 38144365, 2023). "The subjects with diagnosed obesity had significantly higher levels of biochemical parameters, such as total cholesterol, triglycerides, LDL-C, insulin levels, and HOMA-IR index, and lower HDL-C levels than participants at normal weight." (PMID 37887427, 2023). "In summary, LR prevented HFD-induced increase of plasma insulin and adrenal gland weight in C57BL/6N female mice with established obesity and modulated HFD-induced hyperactivity." (PMID 37881580, 2023). "Leptin is one of the obesity adipokines that accelerate the proliferation of CRC and also elevates insulin concentration." (PMID 36982300, 2023). "Obesity (HFD and Lepob/ob-induced) enhances basal (fasting) levels of insulin in circulation in mice." (PMID 37648285, 2023). "In all forms of obesity, there is also a decrease in the level of glucose transporter type 4 (GLUT4), which is the main factor affecting the impairment of insulin-stimulated glucose transport in adipocytes." (PMID 37373485, 2023). "More importantly, the UFA diets improved the obesity-induced impairment of intraperitoneal GTT and ITT, indicating their beneficial role in insulin sensitivity." (PMID 37513618, 2023). "If we consider the in-depth insulin response recorded during an OGTT, the insulin response is doubled in children with obesity to the same amount of glucose when compared to normal weight children." (PMID 36534178, 2023). "Those with obesity and IR exhibit increased GATA-3 expression when compared to insulin-sensitive individuals with BMI matches." (PMID 37056675, 2023). "The main insulin-regulating mechanism affected by ADIPO is the IRS, whose functioning is impaired in obesity." (PMID 37238721, 2023). "Increased meta-inflammation and oxidative stress are the classical hallmarks of obesity and are related to lower SOD enzyme expression and activity in several insulin-sensitive tissues, such as kidney, liver, adipose tissue, and SKM." (PMID 37627494, 2023). "Studies in obesity and T2DM have revealed the correlation of proinflammatory signaling pathways and insulin sensitivity." (PMID 36333974, 2023). "Since the short-chain fatty acids (SCFAs) are released by the gut microbiome, the alteration of microbiome composition in obesity and T2DM disrupts SCFA production and affects insulin sensitivity and energy metabolism." (PMID 37152942, 2023). "In obesity condition, the increased serum level of free fatty acids (FFA) alleviated the insulin‐induced glucose uptake by cells and also insulin resistance phenomenon." (PMID 37329278, 2023). "Obesity, which is common in people with T2DM, is highly correlated with greater BMD, most likely due to mechanical loading and hormonal factors such as insulin, estrogen, and leptin, as well as other hormonal factors." (PMID 37885541, 2023). "At 1 year after anti-obesity treatments, there was a significant reduction in BW (average PWL = 5%), BMI and WC, and a significant improvement in glycemia, insulin sensitivity indices, and CRP levels." (PMID 37436597, 2023). "In conclusion, data of the report revealed that geraniol improved the insulin sensitivity and reduced obesity by promoting the conversion of WAT to BAT in HFD induced obesity in rats." (PMID 38052812, 2023).
Obesity (continued). "Therefore, it seems that the exact mechanism of action of MFSD14B and its function are not yet fully understood, but rs7863750 and the overexpression of MFSD14B may have a role in obesity, as this protein seems to be involved in the regulation of glucose metabolism and insulin signaling." (PMID 37107557, 2023). "Although a HFD induced obesity and abnormal glucose metabolism, HFD‐fed SSTR5 KO mice showed significantly decreased PG, plasma insulin, and GHb levels compared with HFD‐fed WT mice." (PMID 36585794, 2023). "Given the evolution of GLP-1 receptor agonist drugs, the pharmacological harnessing of this ‘incretin effect’ that underpins meal-stimulated insulin secretion is an avenue that continues to be explored in the treatment of T2DM and obesity." (PMID 37249754, 2023). "An adipose tissue-specific Notch signaling null model also exhibited resistance to diet-induced obesity and elevated WAT browning, UCP1 expression, energy expenditure, and insulin sensitivity." (PMID 36674862, 2023). "In obesity, ET-1 tends to be elevated, resulting in vasoconstriction, adipocyte lipolysis due to hormone sensitive lipase (HSL) phosphorylation, insulin resistance, and endothelial inflammation." (PMID 36766750, 2023). "The most studied obesity mouse models, the ob/ob mice, have elevated UCP2 expression and impaired insulin secretion." (PMID 35323702, 2022). "Our data indicated that secretion of adipose tissues from obesity with TNBC and co-incubation with insulin-resistant 3T3-L1 adipocytes promoted proliferation and migration of TNBC cell lines." (PMID 35964108, 2022). "Another important point is the regulation of the renin angiotensin aldosterone system (RAAS) by excess VAT and circulating insulin in obesity leading to an inappropriate activation of tissue and systemic RAAS in obesity." (PMID 35464084, 2022). "Interventions that address mitochondrial inflexibility and insulin resistance are promising for alleviating metabolic and muscle impairments found in HFD-induced obesity." (PMID 36613864, 2022). "Consistent with this notion, chemical depletion of macrophages in the liver mitigates hepatic inflammation, contributing to the improvement of insulin sensitivity and prevention of NAFL in mice with dietary obesity." (PMID 35700043, 2022). "Based on our results, intake of EF-2001 significantly prevented HFD-induced obesity in rats through inhibition of C/EBP-α and PPAR-γ in the insulin signaling pathway on lipid accumulation." (PMID 35334965, 2022). "By contrast, as a result of decreased Vsig4 expression, islets from individuals with obesity exhibited worse GSIS and cellular insulin content after treatment with obese mEVs." (PMID 35091566, 2022). "The observations that RAGE plays roles in diet-induced obesity and NAFLD have important implications for the development of insulin and glucose intolerance, thereby bringing roles for the RAGE pathway in cardiometabolic dysfunction to full circle." (PMID 35811725, 2022). "Therefore, we do not know whether the alterations in insulin kinetics associated with the different types of dysglycemia we observed in people with obesity are also present in lean people." (PMID 34905513, 2022). "Dysregulation of the insulin/IGF system, which is common in overweight and obesity, has been shown to influence breast cancer development via endocrine, paracrine, or autocrine signaling pathways." (PMID 36401194, 2022). "RAC1 is expressed in insulin-sensitive tissues, including AT and skeletal muscle, while activated RAC1 induces oxidative stress in β-cells in obesity." (PMID 35885044, 2022). "As East Asian people are well known to show less insulin secretion than white people, hyperinsulinemia and GIP signaling would contribute to obesity differently between them." (PMID 35452190, 2022).